IL18 (interleukin 18)
Diseases named in the same sentence as IL18 in open-access papers (continued):
Sharing a sentence is not in itself a finding about the gene and the disease.
infection (continued). "Prior to this study, the role of inflammsome activating proteins important for IL-1β/IL-18 responses in mice following infection with Ft strains other than Fn was essentially unknown." (PMID 27926940, 2016). "Interestingly, mice inoculated with T. cruzi displayed elevated IL-18 levels 6 days after infection followed by an increase of IL-12 and IFNγ." (PMID 27027876, 2016). "In particular IFN-γ and IL-18 were continuously increased during the course of infection; both cytokines could therefore potentially function as predictive markers of disease progression and disease severity in this mouse model." (PMID 27163257, 2016). "Moreover, the susceptibility to T. cruzi depends on the capability of releasing IFN-γ during early stages of infection and this is directly related to release of IL-18 during this phase." (PMID 27027876, 2016). "IL18 is a Caspase-1-dependent inflammatory cytokine induced by infection with C. trachomatis." (PMID 26808832, 2016). "Thus, IL-18-elicited NK cell perforin responses seem to be critical for coordinating mucosal inflammation during early infection, when S.Tm strongly relies on virulence factors detectable by the inflammasome." (PMID 27341123, 2016). "This hypothesis was confirmed by the observation that administration of recombinant IFNβ to Il-18-/- mice during the first 6 days of infection completely rescued their survival." (PMID 25768794, 2015). "In addition, the expression of IL-1β, IL-18 and caspase-1 p10 was gradually increased and remained elevated until 7 h of infection." (PMID 26683708, 2015). "THP-1 cells or monocyte-derived Mø produce IL-1β and IL-18 after infection with HCV." (PMID 26549942, 2015). "In this study, we show that IL-1β/IL-18 cytokine activation occurs early after bacteria enter the lung, and this activation eventually contributes to pulmonary inflammation and pathology during the later stages of infection." (PMID 25781467, 2015). "Furthermore, it suggests the possibility that infection and sustained production of inflammatory cytokines, including IL-1β, IL-18, and IL-17, through lipid peroxidation results in chronic inflammation." (PMID 26783845, 2015). "Following challenge with P. gingivalis at a multiplicity of infection (MOI) of 100, expression of the genes encoding NLRP3 and NLRP1 was increased, but with the gene encoding ASC being discordant and the gene encoding pro-IL-18 was downregulated." (PMID 25866631, 2014). "This indicates that IL-18 is constitutively produced within the liver, and that the IL-18 produced before the infection might be processed within the liver and/or diluted in the serum to undetectable levels." (PMID 24824897, 2014). "Here we show that during the host response to infection, different stimuli may trigger different iNKT cell effector programs characteristic of NK cells (e.g. activation by IL-12 and IL-18) or T cells (e.g. TCR activation)." (PMID 24391492, 2014). "In contrast, cytokines generally induced in the later stage of acute pathogenic infection, such as IL-6, IL-18 and TNF-α, were less or not increased, suggesting an early control of IA." (PMID 24991927, 2014). "Despite this significant limitation, the results reported here support the direct infection of at least a sub-set of white blood cells, and suggest that further investigation of inflammasome activation and the presence of IL-1β and IL-18 in CHIKF patients is warranted." (PMID 24721947, 2014). "In Asc−/− mice IL-18 remained undetectable during the course of infection." (PMID 25115174, 2014). "Expression levels of interleukin (IL)-4, IL-10, IL-13 and tumor necrosis factor (TNF)-α were significantly up-regulated while interferon (IFN)-α, IFN-β, IFN-γ, IL-1β,IL-2, IL-3, IL-15, IL-17F, IL-18 and colony-stimulating factor (CSF)-1 were markedly decreased in PBMCs at all stages of infection." (PMID 24358317, 2013).
infection (continued). "In the present study, we have shown that IL-1α, IL-1β and IL-18 were released by NHBE cells following HRV14 infection, and that endogenous IL-1 signaling was essential for the induction and production of a number of pro-inflammatory mediators in response to the virus." (PMID 23723976, 2013). "Moreover the data from our human lung tissue infection model show that NTHi stimulates caspase-1 expression and leads to a strong release of IL-1 family cytokines IL-1β and IL-18." (PMID 23840534, 2013). "We have previously shown that lethal ehrlichiosis in mice is associated with increased il-18 production relative to nonlethal infection, suggesting inflammasome activation." (PMID 23526993, 2013). "those that are down-regulated by infection with virulent S. flexneri (IL-18); iii." (PMID 22675469, 2012). "Interestingly, infection by virulent S. flexneri also led to a significant decrease (2.0 fold, p<0.01) in IL-18 at the late time point." (PMID 22675469, 2012). "IL-18 was only significantly elevated during the middle and late phase of the infection." (PMID 23323093, 2012). "In this malarial model, all the pro-inflammatory cytokines, TNFα, IFNγ, IL-1, IL-6 and IL-18 and the anti-inflammatory cytokine IL-10, were significantly elevated in the plasma throughout the infection with the highest level recorded during the late critical stage." (PMID 23323093, 2012). "Another cytokine shown to induce IFN-γ production during infections is IL-18." (PMID 22206036, 2011). "It is conceivable that this inflammasome-independent production of IL-18 may be sufficient to provide some level of protection to Asc-/- and Nlrp3-/- mice against infection with low B. pseudomallei CFU." (PMID 22241982, 2011). "Confirming the different susceptibilities of Il-18-/- and Il-1r1-/- mice to melioidosis, the bacterial burdens observed in the lungs, spleens, livers, and BALF of infected Il-18-/- mice were dramatically higher than that of WT mice even at early time points (24 hours post infection)." (PMID 22241982, 2011). "Thus, IL-18 concentrations in HIV-infected persons are likely to play an important role in the development and progression of the infection toward AIDS and associated clinical conditions." (PMID 20113500, 2010). "In the absence of infection IL-18 deficient mice also showed diminished stress-induced morphological microglial hypertrophy." (PMID 20113500, 2010). "Moreover, literature suggests glial cells as the main source of IL-18 upon various stimuli, including infection with JEV and WNV (Verma et." (PMID 21034511, 2010). "Infection of Mφ1 with live Salmonella resulted in the production of IL-23, IL-18 and IL-1β." (PMID 20027291, 2009). "While the interaction between NK receptors and ligands expressed on the surface of target cells has been shown to modulate the effector function of NK cells 2, 3 following infection, pro-inflammatory cytokines such as IL-12 and IL-18 are thought to regulate NK cell activation 4–6." (PMID 17407097, 2007). "However, BALB/c splenocytes produced higher proinflammatory cytokines such as IL-1β, TNF-α, IL-6, IL-18 than C57BL/6 splenocytes after infection with B. pseudomallei." (PMID 16919160, 2006). "While it promotes IL-18 and IL-1β secretion, which may help control the infection, it can also lead to harmful outcomes—such as increased neutrophil recruitment and a TH2-biased immune response—that support parasite survival, particularly in L. major infection." (PMID 40794782, 2025). "Caspase-1 catalyzes the conversion of pro-inflammatory cytokines, such as IL-1β and IL-18, into their biologically active forms, which are then released from the cell to initiate inflammatory responses and recruit immune cells to the location of infection or damage." (PMID 40784044, 2025).
infection (continued). "Similarly, in a model of primary HLH induced in perforin-deficient mice by infection with lymphocytic or mouse choriomeningitis virus, the genetic removal of ASC or caspase-1 failed to prevent HLH lethality despite a large reduction in IL-18 levels." (PMID 40632844, 2025). "However, the role of this inflammasome-dependent pathway in other accessory cells, such as dendritic cells or endothelial cells, which might also produce IL-18 upon infection and then co-stimulate Vδ2 T cells, remains to be addressed in further studies." (PMID 41306552, 2025). "We also assessed whether Nlrp6 impacted infection-induced IL-18 and IL-22 release." (PMID 39428744, 2024). "Furthermore, whether NLRP3 inflammasome assembling is required during in vivo infection with T. crassiceps must properly be studied, since we found that both IL-1β and IL-18 are differentially released during T. crassiceps infection." (PMID 38842647, 2024). "Furthermore, the distinct cytokine profile of dogs that have seroconverted raises important questions about the disease status and infection outcomes in such conditions that may be driven by differences in IL-18 production." (PMID 39860978, 2024). "We hypothesized that TOXO immunoglobulin G (IgG) seropositivity, reflecting previous infection and current latency, is associated with increased circulating neuron-specific enolase (NSE), a marker of brain damage, and interleukin-18 (IL-18), an innate immune marker, mainly in SMI." (PMID 38438515, 2024). "Hence, during the early phase of infection, IL-22 can unidirectionally upregulate IL-18 levels at the primary site of infection, allowing IL-18 to promote goblet cell maturation and subsequent mucin secretion, potentially to help flush S. Typhimurium down the GI tract." (PMID 39428744, 2024). "Pretreatment of Caco-2 cells with the pan-caspase inhibitor Z-VAD(OH)-FMK (ZVAD) prior to infection with Δ6 Yptb completely abrogated IL-18 release and cell death compared to the vehicle control, indicating that caspases mediate inflammasome activation downstream of Δ6 Yptb infection in human IECs." (PMID 37615436, 2023). "Several studies analyzed infections (particularly viral), metabolic and inflammatory diseases (adult-onset Still’s disease, systemic juvenile idiopathic arthritis, hemophagocytic lympho-histiocytosis/macrophage activation syndrome) where IL-18 is an important actor of the host response." (PMID 36385417, 2023). "To test whether macrophages could produce soluble signals required to activate NK cells during infection, we established an in vitro model to mimic L. monocytogenes infection in macrophages and measured IL‐1β and IL‐18 secretion in the supernatant of infected cells." (PMID 36861806, 2023). "Therefore, extracellular activation of IL-18 by SpeB may be most important within the skin, giving an implicit role in priming early innate and adaptive immune responses to infection." (PMID 37068092, 2023). "Nevertheless, this does not prove causality and may simply reflect IL-18 production by the mononuclear cells recruited to the site of infection." (PMID 37365163, 2023). "IL-18 may be a defensive cytokine that protects the mother from infection and terminates pregnancy." (PMID 37571360, 2023). "Again, similar levels of cell death and IL-18 release were observed in WT and IRF1-deficient BMDMs in response to infection with E. coli and C. rodentium, whereas BMDMs deficient in caspase-11 had no cell death and impaired IL-18 release in response to these infections." (PMID 37557956, 2023). "Each of these characteristics may be available at bedside in parallel of the assessment of infection, organ dysfunction, pro- (for example TNFα and/or IL-18) and anti-inflammatory (for example IL-1Ra and/or IL-10) cytokines, and markers of adaptive function (for example HLA-DR)." (PMID 36301921, 2022).
infection (continued). "Inflammatory cell infiltration in the lamina propria was detected in the intestine of P. vivax-infected pigeons as early as 2 dpi, which could be related to the higher expression of inflammatory cytokines (IL-1, IL-6, and IL-18) in the intestine during early infection." (PMID 36187827, 2022). "As the study has shown, GSDMD deficiency reduces the secretion of IL-1β and IL-18 in not all infections, so whether GSDMD can promote the protective inflammatory triggered by pro-inflammatory cytokines (such as IL-1β and IL-18) in vivo after SEZ infection remains to be further studied." (PMID 36311722, 2022). "Furthermore, following OLTx with AAV8-Luc, the amount of IL-18 mRNA was considerably higher (p < 0.01) and infection of AAV8-Il18bp could decrease the IL-18 mRNA level (p < 0.05)." (PMID 36551229, 2022). "Therefore, it will be of interest to explore whether IL-18 plays a role in regulating ILCP/ILCs under specific conditions of infection or disease in the future." (PMID 35874724, 2022). "In addition, serum IL-18 was significantly increased after OLTx with AAV8-Luc (p < 0.001), and infection of AAV8-Il18bp could decrease the IL-18 level (p < 0.05)." (PMID 36551229, 2022). "As in this recently mentioned case, the infection was followed by an endless NK activation due to continuously released IL-18 without its sequestering by the loss of IL-18BP function causing cytotoxicity for healthy hepatic cells, thus disrupting immunity, and establishing toxicity and lethality." (PMID 35885055, 2022). "Mice infected with a recombinant RSV expressing IL-18 to enhance NK cell activation had reduced lung viral loads compared to wild-type infection and exhibited biphasic weight loss (days 2 and 6) not observed in wild-type mouse infection." (PMID 34960746, 2021). "Currently, interleukin-18 inhibitors are being investigated as a means of preventing auto-immune diseases; however, this study suggests that like other immunosuppressant biologics, they might have adverse effects on some specific infections." (PMID 34911594, 2021). "Type II IFN is produced both in the early stages of infection by NK cells or macrophages and at later stages by activated T lymphocytes, either via receptor-mediated stimulation (through T or NK cell receptors) or in response to early produced cytokines, such as IL-12, IL-18, and IFN-α/β." (PMID 34517008, 2021). "Moreover, patients with active paracoccidioidomycosis presenting with high levels of IL-1β and IL-18 in the serum that return to normal levels in response to antifungal therapy indicate that these cytokines are released during active infection with this pathogen." (PMID 34769275, 2021). "However, IL-18 levels and MAIT cell activation are linked to infection severity." (PMID 34840991, 2021). "Additionally, during S. Typhimurium infection, IL-18 plays a vital for induction of inflammation within the first 12 h of infection and recruits neutrophil and mature natural killer (NK) cells to the site of infection." (PMID 33203384, 2020). "Further, they support the hypothesis that replication competent HSV-1 is capable of decreasing both AIM2 and NLRP3 dependent inflammasome activation because UV irradiating the virus led to significant increases in IL-18 release in both the ΔAIM2 and ΔNLRP3 lines at 24 hours post-infection." (PMID 32101570, 2020). "The present data suggest a novel role of IL18-607 C/A SNP as a contributor to a more favorable outcome of this disease, potentially leading to a more balanced and more efficient cellular response for the control of fungal dissemination at the early stages of infection in UC." (PMID 33117339, 2020). "Therefore, we hypothesized that IL-18 levels in the gut promoted early innate defenses to infection, while priming mucosal IFNγ to mediate pathogen clearance in the later stages." (PMID 32330185, 2020). "However, the administration of IL-18 inhibited Th2 cytokine production and prolonged infection." (PMID 30717382, 2019).
infection (continued). "Indeed, we could detect significantly elevated levels of several cytokines known to promote NK cell activation during the acute phase of infection, including IL-18." (PMID 31467285, 2019). "In addition, IL-1β and IL-18 are IL-1 family members, could contribute to the development of T cell responses, and shape adaptive immune response during infection." (PMID 30105037, 2018). "Thus, MCV may secrete a GAG-binding vIL-18BP to block IL-18 activity around the site of infection, where virus replication takes place, but also produces a non-GAG-binding form of this inhibitor that could exert its function at more distant sites." (PMID 29946427, 2018). "In chickens, activated macrophages produce a variety of pro-inflammatory cytokines, and modulation of the inflammatory reaction via the upregulation of a few inflammatory cytokines (IL-1β, IL-6, IL-8, and IL-18) might contribute to bursa lesions after vvIBDV infection." (PMID 28086922, 2017). "In another study using a murine model of systemic PCM induced by intravenous infection, the susceptibility of NLRP3 and caspase-1 knockout mice to P. brasiliensis infection was evaluated and their increased susceptibility was associated with reduced IL-18 production and Th1 immunity." (PMID 28740491, 2017). "On the other hand, we could only detect IL-18 at a later time point of infection, at day 13 pi." (PMID 28895840, 2017). "Moreover, following peroral infection of conventional adult mice with Arcobacter butzleri sharing taxonomic relationships to Campylobacterales, cytokines of the IL-23/IL-22/IL-18 axis were regulated not only in a strain and time course of infection, but also tissue dependent fashion." (PMID 27385977, 2016). "In addition, among genes whose transcription was increased by more than log2 1.5 in expression in the day 10 post infection NK cells compared to NK cells of uninfected mice was that for IL-18bp (IL-18 binding protein), which prevents IL-18 engaging the IL-18R on NK cells." (PMID 27403737, 2016). "The ability of IL-18 to rapidly augment expression of its own receptor is suggestive of a positive feedback loop, allowing for enhanced IL-18 signaling, continued synergism with other signaling pathways and efficient induction of NK cell effector functions in the first few hours of infection." (PMID 27047490, 2016). "However, by comparison, the role of IL-1β and IL-18 in this infection has been somewhat neglected and remains unclear." (PMID 25768794, 2015). "On-going infection or inflammatory diseases could lead to transiently higher IL-18 levels." (PMID 26669254, 2015). "The levels of IL-18 in the liver were clearly augmented at 6 weeks PI, suggesting that S. mansoni infection elicited the production of IL-18 within the liver, where and when T cells acquire the potential to produce uncommon combinations of cytokines during the infection." (PMID 24824897, 2014). "However, Itk−/− mice can secrete IFNγ in response to innate stimuli, such as IL-12/IL-18, perhaps this may explain the apparent Th1 sparing reported in some infection studies." (PMID 25250764, 2014). "Therefore, we tested whether the infection of the iacP mutant strain expressing two flagellin subtypes (FljB and FliC) could induce the release of proinflammatory cytokines such as IL-18 and IL-1β in the RAW 264.7 macrophage cell line." (PMID 24069357, 2013). "The differential expression level of MR may determine the differential infection rate because of its strong binding to DV, while the distinct regulation of inflammasome activation in M-Mφ and GM-Mφ contribute to the differential production of IL-1β and IL-18." (PMID 23742038, 2013). "Infection of NHBE cells by HRV is thus likely associated with recognition of viral products, oligomerisation of the inflammasome resulting in caspase-1 activation and release of mature IL-1β and IL-18, but also an alternative active process resulting in IL-1α release." (PMID 23723976, 2013).